RNU7-196P (RNA, U7 small nuclear 196 pseudogene)
Gene: Small nuclear RNA gene on chromosome 5 (73,828,012 to 73,828,073, reverse strand). Ensembl gene ENSG00000238913.
Homologues: Orthologues: chimpanzee U7 (100% identical), macaque U7 (95% identical). Paralogues in human: RNU7-14P (82% identical), RNU7-190P (81% identical), RNU7-40P (81% identical), RNU7-18P (79% identical), RNU7-20P (79% identical), RNU7-23P (79% identical), RNU7-25P (79% identical), RNU7-37P (79% identical), RNU7-45P (79% identical), RNU7-4P (79% identical), RNU7-7P (79% identical), RNU7-1 (77% identical), and 142 more.